CASC9 (cancer susceptibility 9)
Diseases named in the same sentence as CASC9 in open-access papers (continued):
Sharing a sentence is not in itself a finding about the gene and the disease.
laryngeal carcinoma (1 paper, 2022). Carcinoma that arises from the laryngeal epithelium. "CASC9 contributes to cellular proliferation by upregulating the glucose transporter 1 gene in laryngeal carcinoma." (PMID 35427373, 2022).
metastatic tumor (1 paper, 2018). "IHC staining using Ki67 antibodies implied that CASC9 could facilitate the proliferation ability of metastatic tumor." (PMID 29511340, 2018). "Therefore, we conclude that CASC9 could increase the proliferation of both primary site and metastatic tumors." (PMID 29511340, 2018).
sarcoma (1 paper, 2023). A usually aggressive malignant neoplasm of the soft tissue or bone. "CASC9, LINC00922, LINC00511, MEG3, MEG8, and SNHG16 were significantly related to the poor prognosis of sarcoma patients." (PMID 36816047, 2023).
tongue squamous cell carcinoma (1 paper, 2020). A squamous cell carcinoma that arises from the tongue. "LncRNA CASC9 is upregulated in tongue squamous cell carcinoma tissues and cells, suggesting that patients have poor prognosis and can influence the malignant process of tongue squamous cell carcinoma by regulating the miR‐423‐5p/SOX12 axis." (PMID 33174687, 2020).
urothelial carcinoma (1 paper, 2019). A malignant neoplasm derived from the transitional epithelium of the urinary tract (urinary bladder, ureter, urethra, or renal pelvis). "(a) Relative expression of CASC9 was determined by RT-qPCR across 16 urothelial carcinoma cell lines compared to the benign urothelial control cell line HBLAK and a primary urothelial cell culture (UEC)." (PMID 31412811, 2019). "By RT-qPCR analysis we furthermore detected stronger CASC9 overexpression in pure SCC of the urinary bladder and mixed urothelial carcinoma with squamous differentiation than in pure urothelial carcinomas." (PMID 31412811, 2019).
tumor (50 papers, 2016 to 2025). "A similar study demonstrated that AKT/mTOR-mediated suppression of autophagy-mediated apoptosis by long noncoding RNA CASC9 is associated with tumor progression in OSCCs." (PMID 35723362, 2022). "In CRC, CASC9 is significantly upregulated, and higher CASC9 is associated with tumor progression and poor outcomes by polyadenylation specificity factor subunit 3 and TGFβ2 mRNA." (PMID 35427373, 2022). "For example, CASC9 was significantly upregulated in ESCC tissues compared with non-tumor tissues and increased CASC9 expression was associated with worse prognosis and distant metastasis in ESCC patients." (PMID 32005028, 2020). "Increasing evidence indicates that the deregulation of long noncoding RNAs (lncRNAs) contributes to tumor initiation and progression; however, little is known about the biological role of cancer susceptibility candidate 9 (CASC9) in CRC." (PMID 31186036, 2019). "High CASC9 expression was significantly associated with tumor localization (p < 0.001), high AJCC Stage (III and IV, p = 0.034) and extracapsular spread (p = 0.020)." (PMID 31412811, 2019). "Upregulated expression was associated with advanced stages, tumor size and poor overall survival suggesting CASC9 as a biomarker for ESCC diagnosis and prognosis." (PMID 31412811, 2019). "In summary, this study found for the first time that increased CASC9 was significantly associated with tumor size, regional lymph node metastasis, clinical stage and overall survival time in OSCC patients." (PMID 30674868, 2019). "Both LUCAT1 and CASC9 were secreted in exosomes, and higher circulating CASC9 levels were associated with tumor size and HCC recurrence after surgery, suggesting its potential usage as putative non-invasive prognostic biomarker of recurrence." (PMID 30416681, 2018). "qRT-PCR analysis indicated that CASC9 expression was positively associated with tumor size and TNM stage, and predicted poor overall survival of ESCC patients." (PMID 28854977, 2017). "The expression levels of CASC9 were associated with increased tumor size, depth of invasion, and number of lymph node metastasis (P < 0.05)." (PMID 28146436, 2017). "We also investigated the association between CASC9 expression and clinicopathological factors of tumor." (PMID 27431358, 2016). "However, as an oncogene in tumor progression, the underlying mechanism allows CASC9 participating in NPC progression remains poorly understood." (PMID 35419295, 2022). "Besides, the expression of CASC9 in OS tumor tissues was associated with tumor size and TMN stage of OS patients." (PMID 36266695, 2022). "This reciprocal repression of miR-195-5p and CASC9 may highlight the importance role of RNA-RNA interaction and clarify the mechanism underlying tumor progression, including tumor growth, migration, invasion, and metastasis." (PMID 35578597, 2022). "As CASC9 expression level associated with the ESCC tumor size significantly, we speculated that CASC9 might contribute to cell growth of ESCC." (PMID 28854977, 2017). "The present study also demonstrated that increased CASC9 in OSCC is significantly associated with tumor size, regional lymph node metastasis, clinical stage, and overall survival time, suggesting that CASC9 may be an effective therapeutic target and prognostic marker in a variety of tumors." (PMID 30674868, 2019). "Increased expression of lncRNA CASC9 promoted tumor progression by suppressing autophagy-mediated cell apoptosis via the AKT/mTOR pathway." (PMID 36739404, 2023). "Hsa-mir-497-5p miRNA has been shown to inhibit tumor cell growth and invasion, and the expression of the CASC9 lncRNA is abnormally elevated in multiple malignancies." (PMID 37559135, 2023). "CASC9 is mainly concentrated in the cytoplasm and significantly upregulated in human tumor tissues including CRC." (PMID 35427373, 2022).
tumor (continued). "First of all, OS tumor tissues (n = 30) and matched adjacent non-tumor tissues (n = 30) were collected in our research, and then, qRT-PCR was proceeded to detect the expressions of CASC9 in these tissues." (PMID 36266695, 2022). "According to the growth curves, tumor growth in the sh-CASC9 group was evidently suppressed compared with control group from the third week after inoculation (P<0.01)." (PMID 35419295, 2022). "The down-regulation of miR-874-3p recovered the reduction in cell invasion and proliferation in vitro which were induced by CASC9 knockdown and delayed the tumor progression in vivo." (PMID 36266695, 2022). "The PCR results of 80 pairs of BCa and adjacent tissues also showed that the expression of CASC9 in tumor tissues was significantly higher than that in adjacent normal tissues." (PMID 35578597, 2022). "Cancer susceptibility candidate 9 (CASC9) is usually high in CRC and associated with advanced tumor-node-metastasis (TNM) stage and poor prognosis." (PMID 35427373, 2022). "CASC9 knockdown significantly inhibited the cell proliferation, migration and invasion in vitro and enhanced the sensitivity of tumor cells to cisplatin and paclitaxel." (PMID 35419295, 2022). "As for OSCC, lncRNA CASC9 promotes tumor progression, but its downstream targeting of the miRNA/mRNA axis is not fully understood." (PMID 34612783, 2021). "CASC9 expression was found to be overexpressed in 417 CRC tumor samples compared with 41 normal tissues." (PMID 34017854, 2021). "In the present study, our data showed that CASC9 was highly expressed in CRC tissues and associated with the tumor-node-metastasis (TNM) stage." (PMID 33298846, 2020). "Our result showed knockdown of CASC9 decreased tumor growth and tumor weight, and increased tumor free survival time." (PMID 32677984, 2020). "Recent studies have shown that CASC9 can regulate the progression of various human neoplasms by functioning as a ceRNA for miRNAs." (PMID 33298846, 2020). "Meanwhile, CASC9 expression was up-regulated in BC tissues compared to paired non-tumor tissues and higher CASC9 expression was positively correlated with advanced T stage and higher histological grade." (PMID 32677984, 2020). "Together, our results suggest that CASC9 is a powerful tumor biomarker, which highlight its potential clinical utility as a promising diagnostic and therapeutic target of BC." (PMID 32677984, 2020). "For instance, the lncRNA cancer susceptibility 9 (CASC9), upregulated in 70% of primary CRC tumors, promotes both CRC tumor growth and resistance to apoptosis." (PMID 33352769, 2020). "One example of such a tumor-specific hypomethylated region was located in the promoter of a well-known ESCC-implicated long noncoding RNA (lncRNA), CASC9." (PMID 32194853, 2020). "In this study, we found that CASC9 was significantly upregulated in CRC tissues and cell lines compared to normal controls and that aberrant expression was associated with the tumor-node-metastasis (TNM) stage of CRC." (PMID 33298846, 2020). "Conversely, ectopic overexpression of the CASC9–202 or − 204 variants promoted CRC cell growth in vitro and tumor formation in vivo, suggesting that the different variants play similar biological roles." (PMID 31186036, 2019). "Meanwhile, the tumor growth of the sh-CASC9 group was slower compared to that of the sh-NC group (P < 0.05)." (PMID 30674868, 2019). "We further measured CASC9 expression in cells found in the tumor microenvironment like mononucleated blood cells, macrophages, normal fibroblasts and cancer-associated fibroblasts." (PMID 31412811, 2019). "RT-qPCR analysis revealed that, compared with the sh-NC group, the mRNA expression level of LC3B and BAX mRNA was increased in the sh-CASC9 tumor tissues, whereas the mRNA expression level of P62 and BCL-2 was decreased (P < 0.05)." (PMID 30674868, 2019). "We therefore think it is unlikely that CASC9 is a general major driver of tumor development or progression." (PMID 31412811, 2019).
tumor (continued). "Expression was particularly upregulated in advanced stages and correlated with tumor size and poor overall survival suggesting CASC9 as a biomarker for ESCC diagnosis and prognosis." (PMID 31412811, 2019). "More importantly, we discovered for the first time that CASC9 regulates autophagy through the AKT/mTOR pathway in tumor cells, promoting autophagy-mediated apoptosis." (PMID 30674868, 2019). "What’s more, CASC9 expression was found to be significantly correlated with tumor size, regional lymph node metastasis and clinical stage of OSCC (P < 0.05)." (PMID 30674868, 2019). "According to ROC curve analysis, tumor specificity of CASC9 was excellent in the TCGA set, with an area under the curve (AUC) of 0.853; for HOTAIR AUC was 0.886." (PMID 31412811, 2019). "CASC9 expression had excellent tumor specificity according to ROC curve analysis, comparable to results reported in ESCC, and high CASC9 expression was significantly associated with high AJCC stage and extracapsular spread, indicating further diagnostic power." (PMID 31412811, 2019). "Functional studies found that siRNA‐mediated CASC9 silencing inhibited the proliferative ability, invasion in vitro, and impaired the tumour growth in vivo." (PMID 30270508, 2018). "Results illustrated that CASC9 silencing impaired the proliferation, invasion in vitro, and inhibited the tumour growth in vivo." (PMID 30270508, 2018). "In fact, in GC tumor specimens, higher expression level of CASC9 correlated well with increased tumor size, depth of tumor invasion, and number of lymph node metastasis, Borrmann 3 or 4 subtypes, poor differentiation, and INFγ infiltrating pattern." (PMID 28146436, 2017). "It is worth noting that Xu and his colleagues didn’t observe a correlation of CASC9 expression with tumor size." (PMID 28854977, 2017). "The results from tissues showed that CASC9 was overexpressed in 68% of the tumor specimens relative to normal tissues, indicating that the upregulation of CASC9 is associated with ESCC development." (PMID 27431358, 2016). "In addition, higher CASC9 and LUCAT1 levels are associated with tumor recurrence and the more aggressive properties of HCC cells." (PMID 38398157, 2024). "Furthermore, high expression of lncRNA CASC9 correlates with worse tumor differentiation, greater depth of primary tumor infiltration, lymph node metastasis, and advanced TNM staging in EC." (PMID 39161590, 2024). "Given its high expression in OC tissues, we hypothesized that CASC9 may play a tumor-promoting role in OC." (PMID 36266695, 2022). "By reviewing literatures, we discovered that CASC9-related researches is still very limited and the role of CASC9 in tumor progression remains unknown." (PMID 35419295, 2022). "After analyzing, we knew that downregulation of lncRNA CASC9 could significantly inhibit xenograft tumor growth." (PMID 35427373, 2022). "Moreover, in vivo experiments showed that the suppressive effect of CASC9 silencing on tumor growth was partly blocked by inhibiting miR-874-3p, suggesting that the effect of CASC9 on OS was partly exerted by regulating the expression of miR-874-3p." (PMID 36266695, 2022). "The tumor size of the sh-CASC9 group was significantly smaller than that of the control group." (PMID 35419295, 2022). "The knockdown of CASC9 inhibited OS tumor volume, size and weight in vivo (P < 0.01)." (PMID 36266695, 2022). "Previous researches showed that CASC9 could act as miRNA sponge to regulate the biological behavior of tumor cells." (PMID 35419295, 2022). "CASC9 expression in tumor might be a novel prognostic biomarker and CASC9 might be a potential therapeutic target for the management of CRC." (PMID 34017854, 2021). "CASC9 knockdown repressed tumor growth and weight, especially in cells treated with gefitinib." (PMID 33056982, 2020). "Furthermore, our further experiments demonstrated that CASC9 deletion inhibited tumor growth and metastasis of BC in vitro and in vivo." (PMID 32677984, 2020).
tumor (continued). "The results showed that CASC9 was significantly overexpressed in tumor tissues." (PMID 33298846, 2020). "To determine whether knockdown of CASC9 affects tumor formation in vivo, we performed an in-vivo tumorigenesis study by subcutaneously injecting shCASC9-HCT-116 or -SW620 cells into nude mice." (PMID 31186036, 2019). "Finally, overexpressed CASC9 has been reported in recent publications to influence proliferation, migration and invasion of tumor cell lines from cancers of esophagus, lung, stomach, and liver." (PMID 31412811, 2019). "Moreover, this increased expression is significantly correlated with tumor size, clinical stage and overall survival time, which indicates that CASC9 plays an important carcinogenic role in various cancers." (PMID 30674868, 2019). "Moreover, in 28 out of 40 (70%) primary CRC tumors, CASC9 was significantly upregulated in tumor samples as compared to matched adjacent normal tissues." (PMID 31186036, 2019). "In addition, CASC9 promoted cell growth and decreased apoptosis in vitro and was required for tumor formation in nude mice in vivo." (PMID 31186036, 2019). "More importantly, we found for the first time that CASC9 regulates autophagy in tumor cells." (PMID 30674868, 2019). "In vivo xenograft mice assay illustrated that CASC9 stable silencing by lentivirus could markedly decreased the tumour volume and weight." (PMID 30270508, 2018). "Therefore, results revealed that CASC9 silencing impaired the proliferation, invasion in vitro, and inhibited the tumour growth in vivo." (PMID 30270508, 2018). "Additionally, CASC9 down-regulation impeded tumor growth in vivo." (PMID 36266695, 2022). "Our findings indicated that knockdown of CASC9 could inhibit xenograft tumor growth." (PMID 35419295, 2022). "In addition, CASC9 depletion suppressed tumor growth in vivo." (PMID 30674868, 2019). "Meanwhile, we noticed that CASC15, CASC8, CASC9, and CASC19 were highly expressed in tumor samples and CASC16 and CASC18 were lowly expressed in tumor tissues." (PMID 40746360, 2025). "Two lncRNAs (CASC9 and LUCAT1) were shown to be upregulated and one (LINC01093) downregulated in tumor tissues." (PMID 38398157, 2024). "Among these, we identified upregulation of several lncRNAs previously connected to tumor progression, including EPIC1, CASC9, and ZFPM2-AS1." (PMID 38493239, 2024). "Both CASC9 and LUCAT1 were produced from the exosomes, and a high CASC9 level was correlated with tumor growth and postoperative HCC recurrence, implying its potential application as a non-invasive predictive biomarker for HCC recurrence." (PMID 37326156, 2023). "LncRNA NBR2 inhibits tumor development by regulating autophagy in HCC, and lncRNA CASC9 activates autophagy-mediated cell death by AKT/mTOR pathway." (PMID 36072894, 2022). "CASC9 knockdown inhibited the proliferation, migration and invasion of NPC cells and enhanced the sensitivity of tumor cells to cisplatin and paclitaxel." (PMID 35419295, 2022). "The functional role of CASC9 in OC was studied using MTT assay, colony formation assay, transwell invasion assay, and xenograft tumor assay." (PMID 36266695, 2022). "Researchers uncovered that the expressions of LncRNAs, UCA1, CASC9, and FAL1 promote tumor progression in OSCC." (PMID 34912458, 2021). "Of note, a number of lncRNAs with broad oncogenic (SNHG12, CASC9, LUCAT1 and PVT1) or tumor suppressor (such as TINCR) function were also identified to be differentially expressed in cSCC25–28." (PMID 32108138, 2020). "In both sets, expression of CASC9 and HOTAIR was low in most normal tissues and often undetectable, but was strongly increased in most tumor samples." (PMID 31412811, 2019). "However, it is unclear whether CASC9 regulates tumor cell autophagy through the AKT/mTOR pathway." (PMID 30674868, 2019). "CASC9 was strongly increased in both MIX and SCC tumor tissues compared to morphologically pure UC and benign control tissues." (PMID 31412811, 2019).